NR5A1 (nuclear receptor subfamily 5 group A member 1)
Diseases named in the same sentence as NR5A1 in open-access papers (continued):
Sharing a sentence is not in itself a finding about the gene and the disease.
spermatogenic failure (3 papers, 2016 to 2025). A male infertility characterized by dirsuption of the process of sperm development from diploid cells into mature haploid spermatozoa. "Genotype–phenotype correlations analysis revealed a significant association between NR5A1 variants and spermatogenic failure, the most frequent clinical feature, present in 60.8 % of patients." (PMID 41386844, 2025).
acromegaly (2 papers, 2022 to 2025). Acromegaly is an acquired disorder related to excessive production of growth hormone (GH) and characterized by progressive somatic disfigurement (mainly involving the face and extremities) and systemic manifestations. "This suggests that NR5A1 regulates a different set of target genes in gonadotroph and Subtype 1 acromegaly-associated tumors." (PMID 40813692, 2025). "We also compared Subtype 1 somatotroph tumors to the other acromegaly-associated tumors (combined Subtypes 2 and 3) and examined the enrichment of DEGs with NR5A1 and POU1F1 regulons." (PMID 40813692, 2025). "Importantly, all the acromegaly-associated Subtype 1 tumors (co-expressing POU1F1 and NR5A1) formed a distinct cluster located closer to the PIT-1 group than to SF-1 tumors, reflecting their much higher similarity to PIT-1-positive than gonadotroph PitNETs." (PMID 40813692, 2025). "Double-positive (PIT-1/SF-1) acromegaly-associated tumors exhibited a TFs activity profile typical of PIT-1–positive rather than SF-1–positive tumors, except for NR5A1, whose activity was shared by double-positive and gonadotroph PitNETs." (PMID 40813692, 2025). "Transcriptomic group 1 includes ~20% of acromegaly patients with GNAS mutations-negative, mainly densely granulated tumors that co-express GIPR and NR5A1 (SF-1)." (PMID 36497102, 2022).
gonadal agenesis (2 papers, 2022 to 2024). A congenital disorder characterized by the complete absence of gonadal tissue. "Among the known genes associated with nonsyndromic 46, XY gonadal agenesis, variants of SRY, NR5A1, and MAP3K1 are the most common." (PMID 38915825, 2024). "Nr5a1 expression closely follows Gata4 and Wt1 expression in the AGP, and global inactivation of Nr5a1 leads to adrenal and gonadal agenesis." (PMID 36430866, 2022).
gonadotrope deficiency (2 papers, 2013 to 2019). "As a consequence, mutations in the human Nr5a1 gene and Nr5a1 knockout in mice lead to gonadotrope deficiency." (PMID 31391075, 2019).
Hypergonadotropic hypogonadism (2 papers, 2024 to 2025). Reduced function of the gonads (testes in males or ovaries in females) associated with excess pituitary gonadotropin secretion and resulting in delayed sexual development and growth delay. "In addition, hypergonadotropic hypogonadism is a possible hormonal phenotype found in patient with NR5A1 mutation." (PMID 38785542, 2024). "Compensated hypergonadotropic hypogonadism, characterized by elevated gonadotropin levels and normal testosterone levels, was detected in two male patients with DSD due to NR5A1 mutation." (PMID 38785542, 2024). "In conclusion, male and female patients with NR5A1 mutations may have conserved pubertal development or abnormalities with several clinical phenotypes from amenorrhea, potential signs of POI, on a spectrum extending to hypergonadotropic hypogonadism." (PMID 38785542, 2024).
hypothyroidism (2 papers, 2014 to 2023). Abnormally low levels of thyroid hormone. "Interesting findings regarding our two patients bearing a NR5A1 mutation are hypothyroidism in one of them and schizophrenia in the other." (PMID 25580123, 2014). "While Kp10 treatment did not reestablish the change in Star and Cyp11a1 expression caused by hypothyroidism, it increased nuclear receptor subfamily 5 group A member 1 (Nr5a1), also named steroidogenic factor 1, which is an important transcription factor for testicular steroidogenesis." (PMID 37798396, 2023).
ovarian carcinoma (2 papers, 2013 to 2019). A malignant neoplasm originating from the surface ovarian epithelium. "hSF1 expression has been found to be significantly lower in ovarian cancer than in normal ovarian tissue and mutations in NR5A1 are associated with primary ovarian insufficiency." (PMID 31744494, 2019). "Steroidogenic factor-1 (SF-1), the product of the NR5A1 gene, is an essential transcription factor that is known to regulate steroidogenesis in ovarian epithelia, including the synthesis of progesterone, a suppressor of ovarian cancer." (PMID 23291911, 2013). "The analysis revealed that many of the embryonic and cell development genes are fairly high expressed in ovarian cancer including FOXL2, GATA4, NR5A1, AMHR2, MAL and WIPF3." (PMID 31744494, 2019).
Adenovirus infections (1 paper, 2006). "Adenovirus infections of bovine theca cells were performed to elucidate the contribition of the two NR5A1 activating functions to the transcriptional regulation of theca cell-specifically expressed genes." (PMID 17176485, 2006).
Alzheimer disease (1 paper, 2025). A progressive, neurodegenerative disease characterized by loss of function and death of nerve cells in several areas of the brain leading to loss of cognitive function such as memory and language. "Additionally, the orthologs of nhr-25(NR5A1 and NR5A2) and unc-62 (MEIS1, MEIS2, MEIS3) were linked to aging-related diseases such as dementia and Alzheimer’s disease." (PMID 40766245, 2025).
atherosclerosis (1 paper, 2012). A disease characterized by the build-up of fatty material and calcium deposition in the arterial wall resulting in partial or complete occlusion of the arterial lumen. "In particular, NR5A1 is known to be a nuclear receptor that regulates the transcription of many genes involved in atherogenesis and PLSCR3 has been proved to be related to atherosclerosis development by animal studies." (PMID 22244445, 2012).
benign ovarian tumors (1 paper, 2013). "Thus, the NR5A1 gene should be screened for somatic mutations by a more comprehensive method (such as sequencing) in both advanced and benign ovarian tumors, especially tumors that show LOH." (PMID 23291911, 2013).
congenital heart disease (1 paper, 2017). A heart disease that is present at birth. "The co-appearance of congenital heart disease and testicular anomalies was found in a family with a GATA4 p.Gly221Arg mutation, thought to disrupt interaction with FOG2 and/or NR5A1, important factors for gonadal development." (PMID 28541271, 2017).
cyst (1 paper, 2010). A sac-like closed membranous structure that may be empty or contain fluid or amorphous material. "Based on the mouse knockout phenotypes, mutations involving the NOBOX, DMRT4, NR5A1 or StAR genes could be associated with cyst formation, however we did not detect mutations in the coding sequences of these genes in any of the cases described here." (PMID 20593028, 2010).
disc degeneration (1 paper, 2022). "We identified four genes (SOX9, FLVCR1, NR5A1 and UCHL1) associated with mitochondrial dysfunction that play an important role in the progress of disc degeneration." (PMID 36267810, 2022).
genitopatellar syndrome (1 paper, 2016). "The presence of ovotestis was described in a 46,XY girl, with the 9q33.3‐q34.1 deletion encompassing NR5A1 and LMX1B genes causing genitopatellar syndrome associated with female external genitalia and clitoromegaly." (PMID 28033660, 2016).
hyposplenism (1 paper, 2025). "The main aim of our study was to evaluate spleen function in French patients with NR5A1 variants by measuring the prevalence and severity of hyposplenism using pRBC." (PMID 41342320, 2025). "This highlights the importance of systematic screening for hyposplenism in patients carrying NR5A1 variants, as well as the application of preventive measures when necessary." (PMID 41342320, 2025). "This study aimed to determine the prevalence and principal features of hyposplenism in a cohort of French patients with NR5A1 variants." (PMID 41342320, 2025). "This suggests that NR5A1 variants may confer risk of hyposplenism independently of gonadal phenotype, reinforcing the need for splenic evaluation in all NR5A1 carriers, including asymptomatic individuals." (PMID 41342320, 2025).
leukemia (1 paper, 2021). A malignant (clonal) hematologic disorder, involving hematopoietic stem cells and characterized by the presence of primitive or atypical myeloid or lymphoid cells in the bone marrow and the blood. "Taken together it is therefore unlikely that the sole inhibition of NR5A1 is causing the observed effects of SID7969543 on KMT2A-r leukemia cell survival." (PMID 35127484, 2021). "To elucidate whether SID7969543 exerted its selective KMT2A-r leukemia cell killing effect through targeting and inhibiting its reported target, the transcription factor NR5A1, we firstly investigated whether the expression of NR5A1 was associated with the occurrence of a KMT2A rearrangement." (PMID 35127484, 2021). "We next assessed whether the drug impacted downstream NR5A1 signaling in treated KMT2A-r leukemia cells." (PMID 35127484, 2021). "We identified SID7969543, an inhibitor of transcription factor Nuclear Receptor Subfamily 5 Group A Member 1 (NR5A1), as a novel selective candidate inhibitor against a subset of KMT2A-r and CALM-AF10 translocated leukemia cells, including cells derived from infants with KMT2A-r leukemia." (PMID 35127484, 2021). "However, siRNA-mediated silencing of NR5A1 expression did not selectively impact the viability of KMT2A-r leukemia cells and thus did not mimic the action of SID7969543 on these cells." (PMID 35127484, 2021). "In addition, another structurally dissimilar inhibitor of NR5A1, the inverse agonist AC-45594, did not display selective cytotoxicity towards KMT2A-r leukemia cells." (PMID 35127484, 2021). "NR5A1 expression was not significantly different between KMT2A-r and KMT2A-wt infant ALL patient samples nor between KMT2A-r and KMT2A-wt leukemia cell lines, and the sensitivity of leukemia cell lines to SID7969543 did not correlate with expression levels of NR5A1." (PMID 35127484, 2021).
Leydig cell tumor (1 paper, 2025). A sex cord-stromal tumor occurring in the testis and rarely in the ovary. "Interestingly, while Nr2f2 is not expressed in non-proliferative mouse fetal Leydig cells, Nr2f2 is expressed in proliferative mouse Leydig cell tumor cell lines, such as MA-10 and MLTC-1, where it cooperates with Nr5a1 to drive the expression of steroidogenic genes." (PMID 40295478, 2025).
liver cancer (1 paper, 2021). An epithelial or non-epithelial malignant neoplasm that arises from the liver. "The results showed that SMAD3 had strong H3K27ac signals in eight common malignant tumor samples, while the NR5A1 only had H3K27ac signals in liver cancer samples." (PMID 34722892, 2021).
meningitis (1 paper, 2025). A disorder characterized by acute inflammation of the meninges of the brain and/or spinal cord. "Among the 34 patients, three developed severe meningitis in adulthood, before the genetic diagnosis of the NR5A1 mutation, which is responsible for hyposplenism." (PMID 41342320, 2025).
pituitary tumor (1 paper, 2020). A benign or malignant neoplasm affecting the pituitary gland. "mRNA isoforms generated by alternative splicing appear to be specific for POU1F1- and NR5A1- derived pituitary tumors and could potentially be used as molecular markers as well as specific targets for molecular therapy." (PMID 33261069, 2020). "Our results underscored the participation of spliceosome components in the molecular machinery of the pituitary tumors pathogenesis derived from POU1F1- and NR5A1-cell lineages and the alteration of the mRNA splicing patterns characteristic to each tumor." (PMID 33261069, 2020).
Primary hypothyroidism (1 paper, 2014). A type of hypothyroidism that results from a defect in the thyroid gland. "Acquired primary hypothyroidism has not been described as a feature of patients with PGD, with or without NR5A1 mutations." (PMID 25580123, 2014).
red blood cell diseases (1 paper, 2025). "We conducted a cross-sectional multicentre ancillary study among 34 patients carrying heterozygous NR5A1 variants within the GR-EX cohort, which includes individuals from families affected by red blood cell diseases." (PMID 41342320, 2025).
renal cell carcinoma (1 paper, 2020). "The NR5A1-derived tumors showed 657 unique proteins that participate in Renal cell carcinoma (CRK, ELOB and PAK3) and Homologous recombination (ATM, BRCC3 and MRE11) among others." (PMID 33261069, 2020).
somatotropinomas (1 paper, 2022). "SF-1 (NR5A1) is a commonly accepted marker of pituitary gonadotroph cell lineage; therefore, its higher expression in group 1 of somatotropinomas requires special attention." (PMID 36497102, 2022).
sterility (1 paper, 2019). "The ovaries of a newborn mice lacking Nr5a1 in GCs are comparable with wild type; however, Nr5a1-deficient adult females lack CL and suffer from sterility." (PMID 31803139, 2019).
Swyer syndrome (1 paper, 2025). "Swyer syndrome may be caused by SRY mutation (10%–15%), FTHL17, STARD8, SOX9, MAP3K1, NR5A1, and desert hedgehog gene (DHH) mutation as well as other unidentified genes." (PMID 41163677, 2025).
Thrombocytosis (1 paper, 2024). Increased numbers of platelets in the peripheral blood. "Thrombocytosis (high platelet count > 450 000/μL) has previously been reported in individuals with DSD due to NR5A1/SF-1 variants, possibly indicating spleen dysfunction." (PMID 39479520, 2024).
tumor (26 papers, 2008 to 2026). "Materials and Methods: A comprehensive search of PubMed, Scopus, and Web of Science databases was conducted, using terms related to NR5A1 mutations, ambiguous genitalia, gonadal dysgenesis, tumor risk, and surgical management." (PMID 41303802, 2025). "The authors suggested more long-term studies to assess tumor risk associated with NR5A1 variants in 46,XY DSD." (PMID 39936125, 2025). "NR5A1+ tumor cells showed the upregulation of genes associated with response to extracellular stimuli and regulation of neuronal death." (PMID 38658971, 2024). "Since the expression of LHB and GNRHR is related to NR5A1 in both Subtype 1 sPitNETs and gonadotroph PitNETs, other genes regulate by this TF turn out to be differentially expressed in these tumor types." (PMID 40813692, 2025). "Given the lifelong implications of NR5A1-related DSD, follow-up should extend into adulthood to monitor endocrine status, reproductive health, tumor risk, and psychosocial well-being." (PMID 41303802, 2025). "To verify the observation that a distinct set of genes is regulated by SF-1 in double-positive somatotroph and gonadotroph PitNETs, we established regulons of NR5A1 in gonadotroph tumor cells and double-positive somatotroph tumor cell independently." (PMID 40813692, 2025). "INHBA-ACVR1B was found to be the top-ranked ligand-receptor pair among CX3CR1+ macrophages and NR5A1+ tumor cells interaction." (PMID 38658971, 2024). "We found that CX3CR1+ macrophages regulated NR5A1+ tumor cells through regulation of signaling receptor pathway and TGF-β stimulus." (PMID 38658971, 2024). "To confirm the role of INHBA on the CX3CR1+ macrophages NR5A1+ tumor cells interaction axis, we treated primary cells and PitNET cell lines with INHBA." (PMID 38658971, 2024). "article, these data provide compelling evidence that in ACC cells NR5A1 and beta-catenin, which are both relevant factors driving tumour malignancy, regulate mostly distinct gene expression programs through different mechanisms." (PMID 38155952, 2023). "Immunohistochemistry analyses identified that PIT1 cell lineage marker dominates in four PitNETs, gonadotroph PitNET marker NR5A1 (SF1) is the most abundant in five tumours and corticotroph cell lineage marker TBX19 (TPIT) has highest expression in one PitNET." (PMID 36026497, 2022). "We measured NR5A1 expression in somatotroph tumors of transcriptomic group 1 and gonadotroph PitNET samples (tumor samples from our previous investigation) with qRT-PCR." (PMID 36497102, 2022). "This difference between the prevalence of NR5A1 methylation in tumor versus normal ovaries is statistically significant (p<0.0001)." (PMID 23291911, 2013). "In NR5A1-related 46,XY DSD, where the degree of gonadal dysgenesis and tumor risk varies according to the specific variant, a similar individualized approach may be warranted." (PMID 41303802, 2025). "NR5A1 regulates other target genes, such as SRY, responsible for testicular differentiation, WT1, and DHH, associated with gonadal abnormalities and increased risk of tumor." (PMID 41303802, 2025). "Importantly, tumor cells from double-positive PIT-1/SF-1 somatotroph tumors were clearly unrelated to the NR5A1/POU1F1 double-positive gonadotroph subcluster cells (Gonado.PIT1) observed in normal adult pituitary." (PMID 40813692, 2025). "Notably, CX3CR1+ macrophages enriched NR5A1+ tumor cells and INHBA-ACVR1B were locationalized closely in the spatial transcriptome of SF1 lineage tissue." (PMID 38658971, 2024). "Furthermore, the expression of anti-tumorigenic genes (ERG2, ERG3, and BTG2) was promoted by the interaction between CX3CR1+ macrophages and NR5A1+ tumor cells through the ligand-receptor INHBA-ACVR1B pair." (PMID 38658971, 2024).